FOXP3 (forkhead box P3)
Diseases named in the same sentence as FOXP3 in open-access papers (continued):
Sharing a sentence is not in itself a finding about the gene and the disease.
tumor (continued). "Treg cells, as the main immunosuppressive cells in mouse and human tumors, are T cell subsets with phenotypic characteristics of CD4+CD25+Foxp3+, which play an important role in regulating the tumor microenvironment and promoting tumor immune avoidance." (PMID 35445056, 2022). "Along with this, most of the studies only focused on the FOXP3 gene as an upstream regulator affecting tumor metastasis." (PMID 36235242, 2022). "Lastly, among all of the tumor-infiltrating immune cell subsets, only Foxp3+/PD-1− Treg cells were elevated, a subset known to be more immunosuppressive than Foxp3+/PD-1+ Treg cells and a phenotype expected to be intrinsically insensitive to anti-PD-1 mAb." (PMID 36537914, 2022). "A lower count of CD4+CD25+Foxp3+ Tregs in SMGs at Day 14 was detected in tumor-bearing Atg5flox/flox mice, while the Treg counts in spleens from mice with different host autophagy capacity were indistinguishable." (PMID 35966597, 2022). "The primary mediator cells in the tumor microenvironment are Tregs, and many studies have investigated FOXP3 expression and the CD8 or other lymphocyte marker ratios in TILs as Treg markers." (PMID 35358193, 2022). "A crucial role in influencing and controlling the local immune response is attributed to tumour-infiltrating FoxP3+ regulatory T cells (Treg)." (PMID 35140715, 2022). "Due to the close relationship between Treg cells and the tumor microenvironment, FOXP3 has been extensively studied in the development and progression of CRC." (PMID 35864528, 2022). "We evaluated intratumoral interrelation between FOXP3+ tumor-infiltrating lymphocytes and other cytokines in TNBC." (PMID 35565267, 2022). "Fifty-five percent of the sample expressed FoxP3 in more than 10% of the tumor cells (45% men, 72% women, p = 0.061)." (PMID 35327512, 2022). "Another study on the immune microenvironment of GC indicated close relationships among the expression of ICOS in Foxp3+ tumor-infiltrating lymphocytes and pDCs, the expression of ICOS-L and TLR9 of pDCs, and H. pylori infection." (PMID 35311157, 2022). "PLAG increased tumor infiltration of CD8 positive cytotoxic T-cell populations while effectively inhibiting the infiltration of neoplastic T-cells such as CD4/FoxP3." (PMID 35787261, 2022). "CD8+ T cells and FoxP3+ T cells are assumed to get recruited everywhere but with higher probability at the IF of the tumor." (PMID 35867773, 2022). "More importantly, our results showed that AIL-treated tumor supernatant inhibited Treg differentiation and Foxp3 expression more significantly after c-Jun overexpression, further suggesting that AIL indeed works by targeting c-Jun." (PMID 36522774, 2022). "Correlations between frequencies of FoxP3+ Tregs and Helios+ T cells in circulation were stronger in advanced tumor stages, compared to early stages (correlation coefficient r = 0.582, p = 0.036 [early]; r = 0.880, p < 0.0001 [advanced])." (PMID 36146549, 2022). "Both of these proteins have been shown to be expressed on tumour-infiltrating regulatory CD4 + FOXP3+ T cells (Treg) and Th1 CD4+ T cells, respectively, suggesting a potential role in immune escape and/or evasion." (PMID 35327375, 2022). "The enhancement of Foxp3 expression leads to tumor progression by activating the Wnt/β-catenin signaling pathway." (PMID 36544523, 2022). "It has been previously reported that the frequency of CD4+CD25+Foxp3+ Treg cells is amplified in the tumor micro-environment and peripheral blood mononuclear cells, indicating that the enhancement of Treg cells is a widespread problem." (PMID 35606804, 2022). "One of several possible immunosuppressive elements in this context were FoxP3+ Tregs, which were thus regarded as an unfavourable prognostic factor in “immune-desert” tumours." (PMID 35140715, 2022).
tumor (continued). "The present study investigated the expression of FOXP3 in tumor tissues from SCC patients in order to assess the molecular association between Tregs and prognosis in East Asian patients with conjunctival SCC." (PMID 35358193, 2022). "As for γδ T cells, Foxp3 was majorly expressed in Vδ1 T cells from tumor-infiltrating lymphocytes (TILs) and contributed to their suppressive function." (PMID 35967422, 2022). "CD4+ FoxP3+ regulatory T (Treg) cells promote tumor growth by inhibiting anti-tumor immune responses and cancer immune surveillance." (PMID 34423375, 2022). "Another parameter that underlines this relationship is the ratio of FoxP3+ and CD8+ cell density, which was significantly increased in “immune-desert” tumours compared to the remaining two phenotypes." (PMID 35140715, 2022). "Infiltrating tumor-microenvironment-regulatory T cells (TME-Tregs) are important as they serve a suppressive function through the transcription factor Forkhead box P3 (Foxp3)." (PMID 36009853, 2022). "FOXP3, which is related to tumor immune microenvironment and immune escape, is also one of hub genes in male TC." (PMID 35174076, 2022). "CAF-S1 subset also can enhance the expression of PD-1 and CTLA-4 at the surface of CD4+ CD25+ FOXP3+ T lymphocytes to participate in the formation of immunosuppressive environment within tumor mass." (PMID 36324128, 2022). "Immunohistochemical detection of FOXP3 protein in tumor tissue showed that its expression was significantly increased." (PMID 36686653, 2022). "Patients with higher CD8+ T cells or FoxP3+ T cells and PD-L1 expression on tumor cells in the pre-treatment specimen had higher OS." (PMID 35566403, 2022). "Within TIL from RencaHA tumor-bearing mice 86 ± 2% of CD25+FoxP3+CD4+ T cells expressed both CD39 and CD73." (PMID 35013519, 2022). "Analogously, CD8+ compared to FOXP3+ cells display different enrichment patterns for specific metabolites, outlining a characteristic “metabolic signature” of pro-tumor or anti-tumor metabolic environment characterizing the T cell response in the TME." (PMID 36619865, 2022). "FOXP3+ regulatory T (Treg) cells play critical roles in establishing the immunosuppressive tumour microenvironment, which is achieved and dynamically maintained with the contribution of various stromal and immune cell subsets." (PMID 36569832, 2022). "In the present study, we investigated the prognostic relevance of FoxP3+ T cell density in RC depending on the degree of inflammation within the tumour." (PMID 35140715, 2022). "Foxp3-expressing regulatory T cells (Tregs) play a role not only in the suppression of immune response against self-antigens but also in tumor progression by inhibiting the antitumor immunity." (PMID 35131860, 2022). "We found that Tregs in normal colon tissues comprise of significantly higher proportions of stable Tregs (FoxP3+Helios+) compared to tumor tissues." (PMID 35804964, 2022). "The treatment with αCD25-m2a reduced the fraction of CD25-expressing cells in the CD4+ T cell compartment, decreased the percentage of CD4+FoxP3+ Tregs, and increased the Teff/Treg ratios in the blood, draining the lymph nodes and tumor." (PMID 35955841, 2022). "In one patient who had a complete response after vaccination but experienced recurrence two years afterward, high infiltration by T cells was found, with a favorable ratio of CD8+/FOXP3+ (forkhead box P3+) Treg cells from the re-resected tumor." (PMID 35456701, 2022). "Both cases have similar number of cancer cells, number of T cells in the blood compartment, CD8+ T cells to FoxP3+ T cells ratio, and T cells in the tumor at the end of the treatment." (PMID 35867773, 2022). "Immunosuppressive FOXP3+ Tregs infiltrate the tumor microenvironment, inhibiting immune attack and thus affecting the response to immunotherapy." (PMID 36135194, 2022).
tumor (continued). "In tumor-adjacent normal tissue, CLDN18.2-postive showed a distinct tumor microenvironment with higher CD4+ FoxP3+ Treg immune cells and CD4+PD-L1+ T cells." (PMID 35811317, 2022). "FoxP3+ regulatory T cells (Treg), a mature T cell subset with regulatory functions, play an important role in immune homeostasis, allergic reaction, tumor immunity, and transplantation tolerance." (PMID 35694296, 2022). "Studies show a connection between the presence of a high number of FOXP3-positive T cells in tumor tissue and a higher potential of disease relapses and overall poor quality of life." (PMID 36326418, 2022). "A comprehensive correlation matrix was created to seek the correlates of DTICs, including CD3+, CD4+, CD8+, CD68+, and FOXP3+ cells in central-tumor and invasive-margin areas." (PMID 35443723, 2022). "In contrast with Treg, CD8+ T cell concentration is lower in PTC patients, and CD8+ T cell/FoxP3+ Treg ratio is inversely correlated with tumor size." (PMID 36293435, 2022). "There is a growing body of evidence that the FOXP3 gene plays a vital role in tumor metastasis, but the reasons for these discrepant results are still unclear." (PMID 36235242, 2022). "In this study, cellular immunity was induced in tumors treated with RT and ICIs; however, simultaneously, FOXP3-positive regulatory T cells (Tregs), which suppress the cellular immunity, were also accumulated in the tumor." (PMID 35763240, 2022). "A B-cell subset expressing activation markers (CD25+CD69+B7-H1+CD81+CD86+) and termed tumour-evoked Bregs (tBreg) induced the generation of Foxp3+Tregs, which inhibited anti-tumour responses." (PMID 35350071, 2022). "MHC class I expression in the tumor cells (median 40 vs. 90, p = 0.280), FOXP3+ tumor area (median 5 vs. 20, p = 0.277), FOXP3+ stroma (median 56 vs. 290, p=0.145), and CD204+ stroma (median 748 vs. 1049, p=0.481) were all lower in the long SD (+) group." (PMID 36698400, 2022). "We relied on 6-color mIHC staining of TMA samples to evaluate the densities of CD8+ T cells, FOXP3+ Treg cells, and PD-1+ and PD-L1+ cells in tumor tissues and adjacent normal tissues." (PMID 35222387, 2022). "The number of FoxP3+ cells was more than three-fold lower in the tumor from EcN(lpp-OVA)-treated mice (P=0.0002)." (PMID 35847919, 2022). "Subsequently, several studies have shown that FOXP3 is also expressed in a series of tumors and influences tumor metastasis by regulating angiogenesis, invasion, and EMT through the abnormal activation of certain signaling pathways." (PMID 36235242, 2022). "The prognostic utility of the CD8/FOXP3 ratio in the tumor microenvironment has been reported in various cancer types, including NSCLC." (PMID 35222387, 2022). "Since Foxp3 contributes to Treg development and activation, knockdown of Foxp3 on Tregs by shRNA successfully suppressed tumor growth." (PMID 36003395, 2022). "In CRC metastatic liver lesions, the composition of the TME is mainly determined by the chemokine and cytokine pattern, and regularly a small number of FOXP3+ Treg and NK cell cells are recruited to the tumor site." (PMID 35463305, 2022). "The study showed that the induced deletion of Irf4 in Foxp3+ cells in MC38 tumor-bearing mice resulted in a significant delay in tumor growth." (PMID 36009853, 2022). "The result of our study also showed an increase in the frequency of stromal FOXP3+ cells with tumor progression from Ta to T2, however, their frequencies decreased in T3." (PMID 36038861, 2022). "An analysis of paired pre- and post-NACT tumor samples from 60 patients with gastric cancer revealed that, whereas the expression of Foxp3 remained unchanged, the expression of CD4, CD8, PD-1, PD-L1, and TIM3 increased dramatically after NACT." (PMID 36439457, 2022). "The effect of abundant Tregs infiltrating tumor tissues such as colorectal cancers (CRCs) is controversial, and some studies have shown that the infiltration of FOXP3+ Tregs in tumor tissue is beneficial to the prognosis of patients." (PMID 35474948, 2022).
tumor (continued). "Increased levels of USP7 were shown to enhance tumor progression by modulating the immunosuppressive functions of Forkhead box P3 (Foxp3)+ T-regulatory (Treg) cells." (PMID 36428632, 2022). "In the majority of the cases analyzed, we found that cells with suppressor phenotypes (i.e., CD163+ and FoxP3+ cells) are abundant in the tumor, only in the presence of high frequencies of cells with cytotoxic effector phenotypes (i.e., CD8+ cells)." (PMID 36551693, 2022). "Tumor-infiltrating Foxp3+ Tregs and CCR4+ cells were increased in cases with BRAFV595E mutation in comparison to that in cases with wild-type BRAF." (PMID 35131860, 2022). "FoxM1 aggravated tumor development, upregulated FoxP3 expression, increased Treg cells, and reduced CD8+ T cells." (PMID 36301031, 2022). "In recent years, studies have found that FOXP3 is expressed in many kinds of tumors and plays different roles in tumors’ biological behaviors, including tumor proliferation, metastasis, drug resistance, and prognosis." (PMID 36235242, 2022). "Among the tumor‐infiltrating effector T cells, regulatory T cells (Tregs) which express Forkhead box P3 (Foxp3), are critical for maintaining immune homeostasis and tolerance and they suppress antitumor immunity." (PMID 36444617, 2022). "At the end of the study, the regulatory T cell response was analyzed through TGF-β and Foxp3 gene expression in the tumor microenvironment, which was reduced in both cohorts as a result of the 2 and 4 mg doses of glucomannan." (PMID 36298611, 2022). "Of note, nCHI3L1 Ab treatment promoted higher CD8+ T cells to FOXP3+ Tregs (CD8+/Treg) ratio infiltrating into the inner tumor regions as compared to the IgG group." (PMID 34987649, 2022). "In the context of the tumor microenvironment, high FoxP3 + staining is a biomarker of immune suppression that favors cancer progression." (PMID 35558070, 2022). "CD4+ T cells are differently involved in tumor occurrence and development, but mainly through immunosuppression, by Foxp3+ Treg cells and cytotoxic T lymphocytes (Tc), memory T lymphocytes, and T helper lymphocytes (Th)." (PMID 35321670, 2022). "Related research findings found that downregulation of FOXP3 inhibited tumor cell invasion by reducing MMP-9 and MMP-2." (PMID 36185217, 2022). "Next, we detected the CD4+ and CD8+ T cell subsets, as well as the dendritic cell marker CD11c and regulatory T cell (Treg) marker FoxP3 expression in spleen tissues and tumor tissues by immunohistochemistry." (PMID 36238646, 2022). "In total, 74 cancer tissues were stained for CD3, CD8, Forkhead box protein 3 (FOXP3), programmed cell death protein‐1 (PD‐1, invasive front, stromal, intra‐epithelial compartments), and programmed death‐ligand 1 (PD‐L1, tumor, immune cells)." (PMID 34954864, 2022). "FOXP3+ Treg cell levels in the peripheral blood of NSCLC patients increase with tumour stage and peak in metastatic patients." (PMID 36569832, 2022). "No conclusion regarding HPV (+) and HPV (−) OPSCC patients and prognostic relevance of Foxp3-positive Treg tumor TIL infiltration have so far been reached." (PMID 35326661, 2022). "We discovered that simultaneous inhibition of the histone methyltransferases G9A and EZH2 activates the CXCL10–CXCR3 axis and increases homing of intratumoral effector lymphocytes and natural killer cells while suppressing tumor-promoting FoxP3+ CD4 T cells." (PMID 35131874, 2022). "Pretreatment biopsies of patients with lower TRG scores post‐nCRT had higher cell densities of CD8+ and FOXP3+ TAICs in the tumor epithelium compartment (p = 0.013 and p = 0.049, linear‐by‐linear trend test)." (PMID 34743329, 2022). "It is possible that SGT-53 treatment downregulates tumor expression of Tgfb, which is a key regulator of the signaling pathways that initiate and maintain FoxP3 expression and the suppressive function in CD4+CD25− precursors." (PMID 36359830, 2022).
tumor (continued). "In tumor tissues, the majority of Tregs co-expressed both FoxP3 and Helios, suggesting higher immunosuppressive potentials than cells with single expressions of FoxP3 or Helios." (PMID 35655158, 2022). "A high expression level of MMP12 in HCC can promote tumor FOXP3+ regulatory T cell infiltration and contribute to a poor prognosis." (PMID 35932027, 2022). "FoxP3‐positive cells also infiltrated to the stroma area in most cases, with a few cases invading the tumor area." (PMID 34319010, 2022). "FOXP3 (forkhead box P3) is a tumor suppressor gene that regulates the transcription of proto-oncogenes and tumor suppressor genes to exert its anti-cancer function." (PMID 36012638, 2022). "We found that in clinical primary tumor tissues, high levels of PRSS2 expression were associate with increased infiltration of FoxP3+ Tregs in radical prostatectomy specimens." (PMID 36575174, 2022). "Multiple studies reported the association between FOXP3+ Treg cells and VEGF in cancer patients and in vivo tumour animal models." (PMID 36569832, 2022). "Mechanistically, there was increased expression of PD-1, FOXP3 (forkhead box P3), and TGFβ1, key players in the tumor immune evasion response, while genes involved in the inflammatory response, such as IL2 and interferon (IFN)γ, were downregulated." (PMID 36233088, 2022). "We found that higher frequencies of CD4+FoxP3+ Tregs in circulation were associated with shorter DFS, implicating the harmful effect of these suppressive cells in inhibiting anti-tumor immune responses in circulation." (PMID 35655158, 2022). "We found that FOXP3 is a good prognostic factor for patients with high IL-33 and TGFb2 in the tumor." (PMID 35565267, 2022). "The presence of lymphocytes expressing CD3, CD8, CD45RO, and FOXP3 markers was histochemically determined in both stromal and intratumoral regions of tumor tissues." (PMID 36038861, 2022). "Considerable research attention has focused on the relationship between the role of local tumor-infiltrating lymphocytes (TILs [CD4+ and/or CD8+ T cells]) associated with FOXP3+ Tregs in the tumor microenvironment and the prognosis of SCC patients." (PMID 35358193, 2022). "It was mainly expressed in the cytoplasm of normal tissues, and FOXP3 promoted tumor migration, invasion, and proliferation by accelerating the secretion of TGF-β." (PMID 36235242, 2022). "In contrast, SC-236, a structural analog of the clinically useful COX-2 inhibitor celecoxib, reduced the expression of Nr4a factors as well as Foxp3 and Ikzf4 in tumor Treg cells." (PMID 35514961, 2022). "Tumor cells express PD-L1 as an adaptive immune mechanism to escape this anti-tumor environment with a high number of CD8+ cells (Immunoscore) or a high CD8+/Foxp3 ratio, consistently analyzed in our review." (PMID 36248987, 2022). "This was consistent with an increase of IL-10 and expression level of FoxP3 in WT mice subjected to MC38 tumor injection, as compared to IL-10 and FoxP3 levels in the GCSFR−/− mice." (PMID 36033452, 2022). "Accordingly, it has been revealed that the percentage of CD4+CD25+Foxp3+ Treg cells is elevated in the tumor micro-environment of the patient with metastatic breast cancer." (PMID 35606804, 2022). "Regulatory T cells play an immunosuppressive role by expressing the transcription factor FoxP3 and promoting tumor progression by inhibiting the antitumor immune response." (PMID 35872842, 2022). "Foxp3 has been described to regulate the expression of several genes involved in carcinogenesis to utilize its tumor suppressor function." (PMID 36009853, 2022). "Changes in TIL and ratio of CD8+ effector to FoxP3+ Tregs (CD8+:FoxP3+) were determined by IHC using baseline and on-treatment tumor samples." (PMID 35288468, 2022). "In the present study, tmCRT/39-272 promoted Foxp3+ Treg infiltration in the tumor tissue by producing more TGF-β by stimulating M2 macrophages." (PMID 36249426, 2022).